ZDHHC21 (zDHHC palmitoyltransferase 21)
Description:
Palmitoyltransferase that catalyzes the addition of palmitate onto various protein substrates. Palmitoylates sex steroid hormone receptors, including ESR1, PGR and AR, thereby regulating their targeting to the plasma membrane. This affects rapid intracellular signaling by sex hormones via ERK and AKT kinases and the generation of cAMP, but does not affect that mediated by their nuclear receptor. Palmitoylates FYN, regulates its localization in hair follicles and plays a key role in epidermal homeostasis and hair follicle differentiation. Through the palmitoylation of PLCB1 and the regulation of PLCB1 downstream signaling may indirectly regulate the function of the endothelial barrier and the adhesion of leukocytes to the endothelium. Also has a palmitoyltransferase activity toward ADRA1D, positively regulating its activity and expression and may thereby play a role in vascular contraction. May also palmitoylate eNOS and LCK (By similarity).
Synonyms: DHHC-21; HSPC097; DNZ1; DHHC21
Tractability: Antibody: UniProt places it where antibodies can reach, with high confidence; its Gene Ontology location is reachable by antibodies, with high confidence; UniProt predicts a signal peptide or a membrane-spanning region. PROTAC: its protein half-life has been measured.
Gene: Protein-coding gene on chromosome 9 (14,586,766 to 14,693,737, reverse strand). Ensembl gene ENSG00000175893.
Subcellular location: Golgi apparatus membrane; Golgi apparatus, cis-Golgi network membrane; Cell membrane
Subcellular location (Human Protein Atlas): Cytosol; Golgi apparatus
Pathways (Reactome):
Metabolism: eNOS activation
Signal Transduction: Extra-nuclear estrogen signaling
Gene Ontology:
Molecular function: palmitoyltransferase activity; protein binding; protein-cysteine S-palmitoyltransferase activity
Biological process: peptidyl-L-cysteine S-palmitoylation; adrenergic receptor signaling pathway; nitric oxide metabolic process; protein targeting to membrane; regulation of establishment of endothelial barrier; regulation of leukocyte adhesion to arterial endothelial cell; regulation of vascular associated smooth muscle contraction
Cellular component: Golgi apparatus; plasma membrane; endoplasmic reticulum; Golgi membrane
Genetic constraint (gnomAD): Loss-of-function variants: 10 observed, 19.79 expected, observed/expected ratio (o/e) 0.51, 90% interval 0.31 to 0.86. The synonymous counts are far from expectation, so gnomAD's model fits this gene poorly and the ratio says little. Missense variants: 192 observed, 195.74 expected, observed/expected ratio (o/e) 0.98, 90% interval 0.87 to 1.11. Synonymous variants: 91 observed, 63.31 expected, observed/expected ratio (o/e) 1.44, 90% interval 1.21 to 1.71.
Homologues: Orthologues: chimpanzee ZDHHC21 (100% identical), macaque ZDHHC21 (99% identical), guinea pig ZDHHC21 (98% identical), pig ZDHHC21 (98% identical), rabbit ZDHHC21 (98% identical), mouse Zdhhc21 (98% identical), rat Zdhhc21 (97% identical), dog ZDHHC21 (80% identical), tropical clawed frog zdhhc21 (60% identical), zebrafish zdhhc21 (32% identical), Caenorhabditis elegans dhhc-7 (27% identical), Drosophila melanogaster Dnz1 (23% identical), and 7 more. Paralogues in human: ZDHHC3 (31% identical), ZDHHC7 (29% identical), ZDHHC6 (24% identical), ZDHHC1 (22% identical), ZDHHC18 (20% identical), ZDHHC20 (20% identical), ZDHHC15 (20% identical), ZDHHC9 (20% identical), ZDHHC14 (20% identical), ZDHHC23 (20% identical), ZDHHC12 (19% identical), ZDHHC19 (18% identical), and 5 more.
Diseases named in the same sentence as ZDHHC21 in open-access papers:
ZDHHC21 is named in the same sentence as 28 diseases in open-access papers, as found by Europe PMC text mining. Sharing a sentence is not in itself a finding about the gene and the disease. The quoted sentences say what the papers report.
breast carcinoma (4 papers, 2016 to 2024). "A previous study found that ZDHHC21 is required for endogenous androgen receptor palmitoylation, membrane localization, and signal transduction in breast cancer cells." (PMID 38195819, 2024). "A previous study has shown that ZDHHC21 mediates endogenous androgen receptor palmitoylation and enhances membrane trafficking in breast cancer cells." (PMID 38195819, 2024). "Few studies have shown the prognostic value of CBWD1, CWC25, IFNA2, KRT27, or ZDHHC21 in breast cancer, and subsequent studies are expected." (PMID 36077687, 2022).
acute myeloid leukemia (3 papers, 2024). Acute myeloid leukemia (AML) is a group of neoplasms arising from precursor cells committed to the myeloid cell-line differentiation. "Depletion of ZDHHC21 induces the differentiation of acute myeloid leukemia cells and weakens their stemness potential." (PMID 38415253, 2024). "In addition, a recent study reported that ZDHHC21 is highly expressed in acute myeloid leukemia cells and mediates AK2 palmitoylation as well as mitochondrial localization to promote cancer development." (PMID 38195819, 2024). "Additionally, zDHHC21 has recently been identified as a critical regulator of oxidative phosphorylation activation in acute myeloid leukemia cells." (PMID 38415253, 2024). "Moreover, a recent study reported that ZDHHC21 could regulate oxidative phosphorylation by mediating adenylate kinase 2 (AK2) S-palmitoylation and induce differentiation block and stemness in acute myeloid leukemia." (PMID 38195819, 2024).
Alzheimer disease (3 papers, 2022 to 2024). A progressive, neurodegenerative disease characterized by loss of function and death of nerve cells in several areas of the brain leading to loss of cognitive function such as memory and language. "Interestingly, both ZDHHC20 and ZDHHC21 have a potential role in the pathogenesis of Alzheimer’s disease, as they can palmitoylate BACE1, Tau and amyloid precursor protein." (PMID 35819139, 2022).
depression (3 papers, 2019 to 2022). "Here the authors show that palmitoylation of 5-HT1AR by the palmitoyltransferase enzyme ZDHHC21 contributes to depression-like behaviour in rodents and might be implicated in major depressive disorder." (PMID 31477731, 2019). "A recent study defined a role for ZDHHC21 in the palmitoylation of serotonergic receptor 5-HT1A and implicated downregulation of ZDHHC21 in the development of major depressive disorder." (PMID 35819139, 2022). "Together with results obtained in palmitoylomics experiments, these combined data provide a direct evidence for ZDHHC21-mediated 5-HT1AR palmitoylation playing a central role in the etiology of depression-like phenotype." (PMID 31477731, 2019). "Two rodent models for depression-like behavior show reduced brain ZDHHC21 expression and attenuated 5-HT1AR palmitoylation." (PMID 31477731, 2019). "We therefore performed additional experiments to directly address the role of ZDHHC21-mediated 5-HT1AR palmitoylation in depression." (PMID 31477731, 2019). "Consistent with the finding in mouse depression model, Zdhhc21 expression level was also reduced in the PFC of rats with depression-like behavior." (PMID 31477731, 2019). "Of importance, PFC-specific ZDHHC21 knockdown triggered depression-like behavioral traits." (PMID 31477731, 2019). "Moreover, selective knock-down of ZDHHC21 in the murine forebrain induced depression-like behavior." (PMID 31477731, 2019).
endothelial dysfunction (3 papers, 2016 to 2023). In vascular diseases, endothelial dysfunction is a systemic pathological state of the endothelium (the inner lining of blood vessels) and can be broadly defined as an imbalance between vasodilating and vasoconstricting substances produced by (or acting on) the endothelium. "The critical role of PLCβ1 in mediating endothelial dysfunction is supported by the data that knockdown of PLCβ1 in Zdhhc21+/+ ECs led to a significantly attenuated TER response to thrombin." (PMID 27653213, 2016).
diffuse large B-cell lymphoma (2 papers, 2024 to 2025). "In diffuse large B-cell lymphoma (DLBCL), ZDHHC21 acts as a tumor suppressor by palmitoylating FASN at Cys1317, reducing FASN stability and fatty acid synthesis." (PMID 40977744, 2025).
osteosarcoma (2 papers, 2021 to 2024). A usually aggressive malignant bone-forming mesenchymal neoplasm, predominantly affecting adolescents and young adults. "Again, we identified nine genes related to differences in immune cell infiltration in osteosarcoma, four of which are SORBS2, BAIAP2L2, SNAPC3 and ZDHHC21 with low abundances and they have higher disease-free survival probability than the group with high abundances." (PMID 34922489, 2021).
cognitive decline (1 paper, 2023). "We also observed that learning and memory were seriously impaired in ZDHHC21T209S/T209S mice, suggesting that activation of FYN signaling induced by the ZDHHC21 mutation was closely associated with cognitive decline." (PMID 37365538, 2023).
Cognitive impairment (1 paper, 2023). Abnormal cognition is characterized by deficits in thinking, reasoning, or remembering. "We discovered that ZDHHC21 p.T209S contributed to AD by enhancing the palmitoylation of FYN and APP, resulting in AD pathology and synaptic dysfunction, ultimately causing cognitive impairment." (PMID 37365538, 2023).
colorectal cancer (1 paper, 2017). A primary or metastatic malignant neoplasm that affects the colon or rectum. "For instance, a model of seven-gene signatures (NHLRC3, ZDHHC21, PRR14L, CCBL1, PTPRB, PNPO and PPIP5K2) was applied to predict OS by dividing colorectal cancer (CRC) patients into low-risk and high-risk groups." (PMID 28827775, 2017).
familial Alzheimer disease (1 paper, 2023). A degenerative disease of the brain that causes gradual loss of memory, judgment, and the ability to function socially. "Recent studies that investigated familial Alzheimer’s disease (FAD) using exome sequencing have revealed the gene variant ZDHHC21 p.T209S." (PMID 38293675, 2023).
glioma (1 paper, 2025). A benign or malignant brain and spinal cord tumor that arises from glial cells (astrocytes, oligodendrocytes, ependymal cells). "Given the conditions, dysregulated palmitoylation modifications on specific zDHHC enzymes likes zDHHC9, zDHHC13, and zDHHC21 are targeted in AD, HD, schizophrenia, and glioma, suggesting as a therapeutic approach." (PMID 40831763, 2025).
leukemia (1 paper, 2024). A malignant (clonal) hematologic disorder, involving hematopoietic stem cells and characterized by the presence of primitive or atypical myeloid or lymphoid cells in the bone marrow and the blood. "Chemical inhibition or genetic suppression of zDHHC21 weakened the stemness potential and induced the myeloid differentiation of drug‐resistant leukemia stem cells, which rely on OXPHOS for survival." (PMID 39429488, 2024). "zDHHC21 inhibition reduced the growth of patient‐derived AML blasts injected in mice and sensitized AML blasts to the cytotoxic effects of chemotherapy in xenograft model of relapsed/refractory leukemia, highlighting the potential of zDHHC21 as a potential therapeutic target in AML." (PMID 39429488, 2024).
lymphoma (1 paper, 2024). A malignant (clonal) proliferation of B- lymphocytes or T- lymphocytes which involves the lymph nodes, bone marrow and/or extranodal sites. "Our study is the first demonstration that LC exhibits anti-tumor activity in lymphoma by targeting palmitoylation and fatty acid synthesis, suggesting that ZDHHC21/FASN axis can potentially be a promising therapeutic target for patients with DLBCL." (PMID 38195819, 2024).
melanoma (1 paper, 2025). A malignant, usually aggressive tumor composed of atypical, neoplastic melanocytes. "Silencing ZDHHC17 or ZDHHC21, however, had no significant impact on CTNND1 palmitoylation or melanoma cell invasion." (PMID 41321310, 2025).
Parkinson disease (1 paper, 2022). A progressive degenerative disorder of the central nervous system characterized by loss of dopamine producing neurons in the substantia nigra and the presence of Lewy bodies in the substantia nigra and locus coeruleus. "In contrast, the projected-palmitoylome of DG granule cells which have the highest expression of Zdhhc21, Zdhhc4, Zdhhc24, and Zdhhc8 generated KEGG pathways related to ‘Ribosome’, ‘Cholinergic synapse’, and ‘Parkinson’s disease’." (PMID 35819139, 2022).
Sepsis (1 paper, 2025). Sepsis is defined as life-threatening organ dysfunction caused by a dysregulated host response to infection. "In ZDHHC21-depleted mice, the number of neutrophils aggregated in lung significantly decreased, further highlighting ZDHHC21’s role in modulating immune responses during sepsis." (PMID 40461967, 2025).
cancer (4 papers, 2021 to 2025). A tumor composed of atypical neoplastic, often pleomorphic cells that invade other tissues. "Next, we assessed the mutation status of ZDHHC21 in cBioPortal for Cancer Genomics dataset and the results suggested that only 1 out of 135 cases (0.74%) showed mutation in ZDHHC21 locus." (PMID 38195819, 2024). "Moreover, we examined the function of ZDHHC7, ZDHHC20 and ZDHHC21 in human organ development and cancer using PubMed in NCBI." (PMID 36286021, 2022). "ZDHHC7 and ZDHHC21 are conserved specific PATs for endogenous palmitoylation of estrogen, progesterone, and androgen receptors, their membrane trafficking and signal transduction, as was shown in cancer cells." (PMID 34769186, 2021).
tumor (4 papers, 2016 to 2024). "The mRNA expression of ZDHHC21 decreased as the tumor developed from stage I to stage II, suggesting a role for ZDHHC21 in the control of LUAD carcinogenesis and development." (PMID 38177255, 2024). "In contrast, tumor growth was significantly accelerated when ZDHHC21 was depleted in SU-DHL-2 cells, and the percentages of Ki-67 positive cells were markedly increased compared with those of the vector cells." (PMID 38195819, 2024). "In this study, we uncovered a novel function of the palmitoyltransferase ZDHHC21 as a tumor suppressor in DLBCL and identified ZDHHC21 as a key regulator of fatty acid synthetase (FASN) S-palmitoylation for the first time." (PMID 38195819, 2024). "Taken together, our results not only reveal a novel biological function of ZDHHC21 as a tumor suppressor in DLBCL and identify it as a key regulator for FASN palmitoylation for the first time but also establish targeting ZDHHC21/FASN axis as a promising therapeutic strategy for patients with DLBCL." (PMID 38195819, 2024). "In addition, decreased tumor weights were observed in ZDHHC21-WT-overexpressing cells." (PMID 38195819, 2024). "However, the same ZDHHC gene may be amplified in some tumor types but deleted in others (e.g. ZDHHC17, ZDHHC20, and ZDHHC21)." (PMID 31938047, 2020).
ZDHHC21 also shares sentences with these, for which no sentence is quoted: systemic inflammatory response syndrome (2 papers); autoimmune lymphoproliferative syndrome (1); inflammation (1); intestinal infections (1); lipoma (1); neuroblastoma (1); schizophrenia (1); Stormorken syndrome (1); tubular aggregate myopathy (1).